TRAJ53 (T cell receptor alpha joining 53)
Gene: T-cell receptor joining (J) gene on chromosome 14 (22,483,004 to 22,483,069, forward strand). Ensembl gene ENSG00000211837.
Diseases named in the same sentence as TRAJ53 in open-access papers:
TRAJ53 is named in the same sentence as 2 diseases in open-access papers, as found by Europe PMC text mining. Sharing a sentence is not in itself a finding about the gene and the disease. The quoted sentences say what the papers report.
primary biliary cholangitis (1 paper, 2025). Primary biliary cholangitis (PBC) is a chronic and slowly progressive cholestatic liver disease of autoimmune etiology characterized by injury of the intrahepatic bile ducts that may eventually lead to liver failure. "For the α chain, Trav10 [S26], Trav16n [S20,26], Trav17 [S27], Trav5‐4 [S26], Traj42 [S20,26] and Traj53 [S26] were associated with Type I diabetes, whereas Trav12‐2 [S28] was associated with primary biliary cholangitis." (PMID 40665793, 2025).
TRAJ53 also shares sentences with these, for which no sentence is quoted: Type I diabetes (1 paper).